ICAM1 (intercellular adhesion molecule 1)
Diseases named in the same sentence as ICAM1 in open-access papers (continued):
Sharing a sentence is not in itself a finding about the gene and the disease.
malaria (118 papers, 2007 to 2025). Malaria is a serious and sometimes fatal disease caused by a parasite that commonly infects a certain type of mosquito which feeds on humans. "Elevated plasma angiopoietin-2 and soluble ICAM-1 are two markers of endothelium activation and increased permeability that were previously associated with malaria severity and risk of cognitive impairment." (PMID 36759905, 2023). "Our work provides systematic genomic and structural insights into ICAM-1 global mutations in context with the likelihood of altered malaria susceptibility across populations." (PMID 38093209, 2023). "In human malaria, direct sequestration of erythrocytes is caused by expression of intercellular adhesion molecule 1 (ICAM-1) on the surface of endothelial cells." (PMID 36839438, 2023). "Further examination of the risk alleles of the ICAM1 SNPs in association with clinical malaria phenotypes, suggests that maternal mutations in rs5490 (A>C) and rs5491 (A>T) increased the risks of malarial anaemia odds ratios of 3.027 and 2.043, respectively)." (PMID 37287037, 2023). "Polymorphism studies in host ICAM-1 via gene sequencing conducted in field isolates collected from malaria patients have shown conflicting clinical manifestations." (PMID 38093209, 2023). "A polymorphism in ICAM1, rs5948 (also known as K469E), has been associated with increased risk of severe malaria in Indian and Nigerian populations." (PMID 37237555, 2023). "Whereas previous work has linked EPCR or dual EPCR and ICAM-1 PfEMP1 variants to severe malaria, little is known about their endothelial binding specificity." (PMID 35155278, 2022). "In the present study, the SNPs of the two host genes involved in immune functions, i.e., TGFβ1 and IL10, and the one involved in malaria parasite binding (ICAM1) were significantly associated with P. falciparum parasitemia." (PMID 34698295, 2021). "ICAM-1 is constitutively expressed on endothelial cells in the gut microvasculature and neutrophils from blood of malaria patients cause endothelial damage in vitro by binding to ICAM-1." (PMID 26830671, 2016). "The ICAM-1 Killifi polymorphism has been associated with both the resistance and susceptibility to severe forms of malaria." (PMID 23316245, 2012). "The ICAM-1 (CD54) is a member of the immunoglobulin super-family, and its role in malaria susceptibility is not limited to an interaction with PfEMP1." (PMID 23316245, 2012). "Particular expression of PfEMP1 variants, with differential ability to bind ICAM-1, has been demonstrated in malaria patients with coma." (PMID 22305466, 2012). "Our results show that increased binding to CD36 is associated with uncomplicated malaria while ICAM-1 adhesion is raised in parasites from cerebral malaria cases." (PMID 21390226, 2011). "ICAM-1 is of interest because its expression on brain endothelium is up-regulated in severe malaria and a natural polymorphism termed ICAM-1Kilifi affects disease severity in some parts of Africa." (PMID 21390226, 2011). "For example, ICAM-1 is markedly up-regulated in severe malaria and has been implicated as being involved in progression to cerebral disease." (PMID 22043276, 2011). "The PFD1235w Plasmodium falciparum erythrocyte membrane protein 1 (PfEMP1) antigen is associated with severe malaria in children and can be expressed on the surface of infected erythrocytes (IE) adhering to ICAM1." (PMID 21078147, 2010). "TNF and ICAM-1 polymorphisms and their association with malaria susceptibility has also been inconsistent across various populations." (PMID 19317913, 2009). "Among isolates that bound to ICAM-1, 40% of isolates causing severe malaria showed major decreases in their binding to both mutant ICAM-1 proteins when compared to their binding levels to ICAM-1Ref." (PMID 19650937, 2009). "The ICAM‐1 Kilifi polymorphism has been found in Kenyan children with severe malaria." (PMID 38099246, 2023).
malaria (continued). "To determine whether ABO genotype might influence malaria susceptibility via these mechanisms, we conducted in vitro experiments examining cytoadhesion to ICAM-1 and CD36 and PfEMP1 display in relation to infected RBC ABO genotype." (PMID 37708213, 2023). "In some studies ICAM-1 expression has been associated with severe falciparum malaria and more severe infections of children, whereas a negative correlation with disease was found in a Malawian childhood malaria study." (PMID 28468674, 2017). "Since parasites from these children show increased binding to CD36 and ICAM-1, the PfEMP1 variants causing uncomplicated malaria in HbAS children might share features with those causing severe malaria in other children." (PMID 24647281, 2014). "Additionally, an ICAM-1 SNP in exon 6 (rs5498, K469E) has been associated with increased risk of severe malaria in Nigeria." (PMID 19055786, 2008). "Interestingly, the ICAM1 SNPs, rs5490, rs5491, and rs5498, have been published as being associated with malaria, a finding which was later scrutinized in a larger meta-analysis, which could not corroborate the earlier findings." (PMID 37287037, 2023). "Apart from cytokine induction, HZ also induced upregulation of ICAM1, a cell adhesion molecule integral to neutrophil trafficking and also implicated in various forms of acute lung injury in addition to its well-known role in severe malaria cytoadherence phenotypes (49, –, 53)." (PMID 33563839, 2021). "Factors associated with severe malaria that may be affected by hydroxyurea in children with SCA include intracellular adhesion molecule-1 (ICAM-1), vascular cellular adhesion molecule-1 (VCAM-1), von Willebrand factor (VWF), tumor necrosis factor-alpha (TNF-α), and nitric oxide (NO)." (PMID 27339303, 2016). "Similarly, the association between ICAM1 polymorphisms seizures with severe malaria could be explained by the binding of ICAM1 to P. falciparum–infected erythrocytes onto brain microvasculature causing sequestration." (PMID 23614351, 2013). "The situation in vivo as to whether levels of soluble VCAM-1 and ICAM-1 are associated with severe malaria is also unclear, but generally the picture is one of a pro-inflammatory disease with concomitant increases in endothelial biomarkers in patients with severe disease." (PMID 22043276, 2011). "Putative ICAM-1-binders were very low or absent at all time points, but we detected statistically significant higher expression of group-B ICAM-1-binders in clinical malaria compared to end-dry season infections." (PMID 40493675, 2025). "It concludes how the PfEMP1 family enables the parasite to evade the immune system through antigenic variation, allowing it to adhere to host receptors such as CD36, ICAM-1, PECAM-1, and EPCR, which are associated with severe malaria." (PMID 40523953, 2025). "In order to activate NK cells during malaria, direct cell-cell contact with other cells via, for example, intercellular adhesion molecule-1 (ICAM-1), and the presence of interleukin (IL)-2, IL-12 and IL-18 in the environment are needed." (PMID 39355242, 2024). "Children with cerebral malaria had higher ADNP of ICAM-1 + CD36 binding IE than children with uncomplicated malaria (4% (2–7%) and 2% (1–3%), respectively, p = 0.025)." (PMID 39267089, 2024). "CD44, CD36 and ICAM1 have been previously reported to play an important role in malaria pathophysiology." (PMID 38828264, 2024). "Children with uncomplicated malaria had higher ADNP of ICAM-1 + EPCR binding IE compared to children with cerebral malaria (median (IQR), 15% (8–34%) and 7% (3–15%), respectively, Wilcoxon signed-rank test p < 0.001)." (PMID 39267089, 2024). "The results herein provide evidence for the association of TLR4 and related genes, ICAM1, IFNGR1, IL13, and IL6, as well as ABO, with the incidence of clinical malaria." (PMID 37287037, 2023).
malaria (continued). "An overlapping set of genes, HP, ICAM1, IFNG, TLR2, and TLR4 were found to contain SNPs statistically significantly associated with malaria in both maternal and child analyses." (PMID 37287037, 2023). "PfEMP1 (P. falciparum erythrocyte membrane protein 1) mediates infected erythrocytes adhesion to various surface vascular receptors, including intercellular adhesion molecule-1 (ICAM-1), associating this interaction with severe malaria in several studies." (PMID 38093209, 2023). "In a recent study, Beninese children with uncomplicated malaria had higher antibodies to a recombinant Group A DBLβ3 and a CIDRα1.4-DBLβ3 couplet (predicted to be dual ICAM-1 and EPCR binding) than children with cerebral malaria." (PMID 36419237, 2023). "ICAM-1 is one of the most common receptors that mediates cytoadherence and is involved to the pathology of malaria, as well as ICAM-4 protein, which plays a role in host cell invasion by P. falciparum." (PMID 37048057, 2023). "ICAM-1 remains a receptor of major interest, and several authors have investigated its role in the pathogenesis of severe malaria." (PMID 35379236, 2022). "Compared to controls, the plasma concentration of soluble form of ICAM-1 is increased in malaria-infected patients." (PMID 35379236, 2022). "Remarkably, ICAM-1 also plays a vital role in various other infectious diseases, including tuberculosis and malaria." (PMID 35316427, 2022). "ICAM1 is another cytoadherence receptor relevant to severe malaria and MA-ALI (49, –, 53) and is also critical for neutrophil trafficking and associated with other forms of acute lung injury." (PMID 33563839, 2021). "Proinflammatory signaling is induced, and key cytoadherence molecules are upregulated, including several associated with severe malaria, such as CD36 and ICAM1." (PMID 33563839, 2021). "PfEMP1 has been found to bind to CD36 on platelets via CIDRα2-6 domains in uncomplicated/mild malaria (UM/MM), and to ICAM-1 on endothelial cells in severe malaria (SM) via DBLβ5 domains." (PMID 32153634, 2020). "Global analysis of the BAFF-var allele on total RNA expression revealed many differentially expressed genes implicated in the immune response to malaria; among them, we selected CXCL10, CR1, MIF, ICAM-1, and NFKB2 for further analysis." (PMID 33123155, 2020). "And, when the binding capacity to CD36, ICAM‐1 or EPCR was investigated, adhesion to EPCR and ICAM‐1 was more common in cerebral malaria‐causing parasites than in uncomplicated malaria‐causing parasites." (PMID 30804082, 2019). "It has been suggested that histamine-secreting basophils activated by IgE through FcεRI increase vaso-permeability and the over-expression of ICAM1 on endothelial cells, suggesting that Th2 lymphocytes promoting the production of IgE play a role in malaria." (PMID 31666081, 2019). "Endothelial receptors have been studied to understand iRBC adherence in the microvasculature of different organs in severe malaria, and some of these receptors are well established such as ICAM-1 in cerebral malaria and CSA in placental malaria." (PMID 31871954, 2019). "PfEMP1-mediated adhesion of IEs to the endothelial receptors ICAM-1 and EPCR have both repeatedly been implicated in the pathogenesis of severe malaria." (PMID 29426042, 2018). "Twenty-two of the isolates (3 from children with uncomplicated malaria, 14 from patients with severe malaria, and 5 from children with cerebral malaria) showed adhesion of IEs to ICAM-1." (PMID 29426042, 2018). "In malaria-infected dams supplemented with L-arginine, we observed reduced gene expression of inflammation-related proteins C5 (P < 0.001) and Icam-1 (P < 0.01)." (PMID 29514999, 2018). "The BOECs were shown to express known P. falciparum-IE adhesins associated with cerebral disease (ICAM-1/CD54 and EPCR/CD201), and levels of expression were altered in response to TNF-α, a cytokine associated with severe malaria." (PMID 30300360, 2018).
malaria (continued). "Malaria iRBCs have been shown to bind to several receptors, of which intercellular adhesion molecule 1 (ICAM-1) upregulation in brain microvasculature is the only one correlated to cerebral malaria." (PMID 28646215, 2017). "In malaria, increased margination and sequestration of neutrophils is explained by the increased expression of cell adhesion molecules (ICAM-1 and VCAM-1)." (PMID 28363279, 2017). "In children with malaria and acute gut injury, adhesion of mature iRBCs to ICAM-1 under static conditions was significantly increased." (PMID 26830671, 2016). "The role of adhesion molecules, especially ICAM-1, in the leukocyte/endothelium interaction to promote cerebral dysfunction during experimental severe malaria is controversial." (PMID 26491221, 2015). "A frequently described PfEMP1 receptor is ICAM-1, and binding of IE to ICAM-1 during infection is linked to the development of symptoms of severe malaria, such as cerebral malaria." (PMID 26320251, 2015). "Conserved epitopes, such as those targeted by 24E9, are promising candidates for the inclusion in a vaccine interfering with ICAM-1–specific adhesion of group A PfEMP1 expressed by P. falciparum IE during severe malaria." (PMID 26320251, 2015). "CM isolates bind significantly more to CD36 than to ICAM-1, which was correlated with high transcription level of group B var genes, supporting their implication in malaria pathogenesis." (PMID 25156105, 2014). "The aim of the study was to find possible associations between the membrane expression of ICAM-1 and the plasma levels of antibodies to CD36- and ICAM-1-binding VSAs on one hand, and the development of cerebral complications in malaria patients." (PMID 24386348, 2013). "ICAM-1 expressed in HEK293 is applicable to malaria research and can also be useful in other research fields." (PMID 23936131, 2013). "ICAM-1 is expressed in low copy number in resting endothelium and is up-regulated in inflammation and infection including severe malaria with coma." (PMID 22305466, 2012). "The high case fatality rate syndromes of cerebral malaria and lactic acidosis were associated with high platelet CD36 expression and thrombocytopenia, and severe malaria anaemia was characterized by low ICAM1 expression." (PMID 22909232, 2012). "Plasmodium falciparum isolates from patients with differing degrees of disease severity show endothelial receptor binding diversity with binding to ICAM-1 highest and most robust in P. falciparum isolates from patients with severe malaria with coma." (PMID 22305466, 2012). "The findings presented here provide a platform from which to focus efforts on blocking or reversing ICAM-1-mediated adhesion to reduce cerebral malaria as well as a reconsideration of anti-CD36 strategies for controlling severe malaria." (PMID 21390226, 2011). "In clinical malaria, increased serum levels of the soluble form of ICAM-1 and increased protein expression in the microvascular endothelial sites have been observed." (PMID 22110737, 2011). "ICAM-1 surface expression was shown to be required for the interferon-γ response of Natural Killer cells to malaria-infected red cells." (PMID 20712868, 2010). "In the meantime, to clarify further the role of ICAM-1 in malaria, measurement of both cell-surface and soluble ICAM-1 are recommended for clinical and laboratory studies of ICAM-1 and malaria." (PMID 20712868, 2010). "Improved understanding of the role of ICAM-1 in the molecular pathology of malaria remains important." (PMID 20712868, 2010). "Consistent with previously published work, soluble ICAM-1 levels were found to be significantly higher among children with severe malaria syndromes or fatal malaria compared to those with uncomplicated malaria." (PMID 20712868, 2010). "In this study children with uncomplicated malaria, treated as outpatients, had significantly higher monocyte ICAM-1 expression than those with severe or fatal disease." (PMID 20712868, 2010).
malaria (continued). "Elevated levels of soluble ICAM-1 (sICAM-1) have previously been reported with increased malaria disease severity." (PMID 20712868, 2010). "Plasma concentrations of angiopoietin-2 (Ang-2), an angiogenic factor stored in WPBs, predict increased mortality in malaria, and ICAM-1 is a major endothelial adhesion receptor mediating cytoadherence of parasitized red cells and microvascular sequestration." (PMID 20421938, 2010). "Laboratory studies also support a role for adhesion of parasitized erythrocytes to ICAM-1 in malaria pathogenesis." (PMID 20712868, 2010). "In this study, plasma and whole blood levels of soluble ICAM-1 followed a log-normal distribution in children with malaria." (PMID 20712868, 2010). "Few clinical studies have examined ICAM-1 expression on circulating monocytes among subjects with malaria." (PMID 20712868, 2010). "Association of the ICAM1 rs5498 (exon 6) G allele and the CD36 exon 1a A allele with increased risk of severe malaria was observed (severe versus control, OR = 1.91 and 2.66, P = 0.02 and 0.0012, respectively)." (PMID 19055786, 2008). "Parasites isolated from severe malaria patients in Thailand were shown to preferentially bind ICAM-1 on lung endothelium in vitro compared to those from uncomplicated patients." (PMID 18483551, 2008). "Severe malaria is associated with sequestration of Plasmodium falciparum-infected red blood cells (PRBC) in the microvasculature and elevation of intercellular adhesion molecule-1 (ICAM-1) and TNF." (PMID 17383656, 2007). "There is strong literature evidence for ICAM1, as well as another gene identified herein, GCLM, and its associated gene, GCLC being potential molecular mediators for the pathology of malaria." (PMID 37287037, 2023). "Although cytokine modulation of ICAM-1 expression is documented in the literature in specific or niche contexts, none have suggested an association pertaining to clinical malaria." (PMID 37287037, 2023). "Another ICAM1 polymorphism, rs5491 (K29M or ICAM-1Kilifi), has been associated with an increased risk of cerebral malaria in Kenyan children and an increased risk of hospitalization due to malaria in Tanzanian children." (PMID 37237555, 2023). "In knowlesi malaria, plasma syndecan-1 was also highest in those with severe disease, and correlated with markers of endothelial activation (angiopoietin-2, osteoprotegerin, ICAM-1), asymmetric dimethylarginine (ADMA) and impaired microvascular reactivity." (PMID 33963210, 2021). "In our transcriptomic data, we also noted upregulation of two other malaria-associated cell adhesion molecules, thrombospondin-1 (THBS1) (Padj < 10−7; log2FC = 0.23 ± 0.04; linear model) and intercellular adhesion molecule-1 (ICAM1) (Padj < 10−4; log2FC = 0.30 ± 0.07; linear model)." (PMID 33563839, 2021). "In a model of infection with Plasmodium berghei ANKA, ICAM-1-deficient mice survived the acute phase of infection, suggesting that a reduction of ICAM-1 may decrease malaria severity." (PMID 33123155, 2020). "The interaction between BAFF and its receptor BAFF-R activates non-canonical NFκB signaling that is closely associated with the secretion of pro-inflammatory cytokines, chemokines, and adhesion molecules such as ICAM-1, which are important in the malaria immune response." (PMID 33123155, 2020). "Sequestration of P. falciparum IEs to the microvascular endothelium contributes to the pathogenesis of severe malaria in children, and broadly, cross-reactive antibodies inhibiting the interaction between ICAM-1 and DBLβ domains are detectable in immune plasma." (PMID 31308082, 2019). "DBLβ3 was also up-regulated; it can bind ICAM1 and is found in—but is not restricted to—severe malaria–associated DC4 and DC8." (PMID 29529020, 2018). "Our recent publication identifying a subset of dual ICAM-1- and EPCR-binding P. falciparum-IEs associated with cerebral malaria indicates that important components in malaria pathogenesis may lie with the endothelium." (PMID 30300360, 2018).